IL6 (interleukin 6)
Diseases named in the same sentence as IL6 in open-access papers (continued):
Sharing a sentence is not in itself a finding about the gene and the disease.
liver fibrosis (continued). "In addition, acute binge drinking has been shown to significantly increase serum bacterial DNA and pro-inflammatory cytokines such as IL-6, TNF-α, and IL-1β to indirectly contribute to liver fibrosis." (PMID 31717860, 2019). "Interestingly, CDH11-/- mice had decreased histological evidence of liver fibrosis, collagen deposition, α-smooth muscle actin (α-SMA) accumulation, and mRNA levels of fibrotic mediators such as Col1-α1, Snail, TGF-β and IL-6." (PMID 31269038, 2019). "The BMSC+VEGF group had decreased collagen deposition, reduced stellate cell activation, and decreased TGFβ and IL-6 expression (inflammation marker), which further suggests that combination of VEGF treatment and BMSC transplant drastically reduces liver fibrosis." (PMID 31885614, 2019). "Noticeably, one of the Stat3 signaling cytokine with pro-fibrogenic properties is IL17A, enhancing activation of hepatic myofibroblasts either directly or through IL6 secretion and collected evidences indicate the contribution of activated STAT3 in liver fibrosis." (PMID 30346985, 2018). "Interleukin 6 (IL6) stimulates the activation of STAT3 and increases collagen mRNA expression in HSCs, thus accelerating liver fibrosis via Stat3 phosphorylation that in turn activates transforming growth factor beta (TGFβ) signaling cascade through SMAD3 activation." (PMID 30346985, 2018). "Also, in vivo in a setting of hepatic fibrosis in rats reduced ALT, AST, IL-6 and HMGB1 values were found after EP treatment compared to the control group accompanied by decreased mRNA levels of TLR4 and NF-κB." (PMID 29420582, 2018). "High concentrations of IL-6 can stimulate hepatocyte apoptosis and HSC proliferation, activate Kupffer cells to secrete more pro-inflammatory cytokines, and promote extracellular matrix synthesis, leading to aggravated liver fibrosis." (PMID 28646179, 2017). "The importance of IL-17F in chronic hepatic diseases was poorly investigated; however, we had found Th-17 associated inflammatory cytokine, IL-17F, which took a major part in severe liver fibrosis and HCC symptoms in HCV patients than other inflammatory cytokines, IL-6, and IL-17A." (PMID 28770001, 2017). "IL-6 is a known pro-inflammatory cytokine that in the presence of increased levels of TGF-β, as in hepatic fibrosis, promotes the differentiation of naiive T lymphocytes to Th17 cells, characterized by autoimmunity and secretion of a pro-inflammatory cytokine profile, including IL-17A." (PMID 29176797, 2017). "IL-6 is a pleiotropic cytokine in modulating inflammatory responses in liver diseases through activation and phosphorylation of both NF-κB and STAT3 proteins, which in turn stimulate progressive liver fibrosis." (PMID 29179490, 2017). "After hanging drop culture for 1, 2, and 3 days, RT-PCR was used to determine the expression levels of cytokines, including insulin growth factor 1 (IGF-1), interleukin-6 (IL-6), and hepatocyte growth factor (HGF), which play important roles during inhibition of hepatic fibrosis." (PMID 27022400, 2016). "Neutralization of IL-9 further suppressed expression of inflammatory cytokines including IL-9, IL-17A, IFN-γ, TGF-β1, IL-6, IL-4 and TNF-α in the mouse model of hepatic fibrosis, suggesting IL-9 may regulate the inflammatory responses to liver fibrosis." (PMID 26728971, 2016). "The results demonstrated that HCV patients with moderate fibrosis (F1-2) presented high frequency of CD8+ T-cells along with lower levels of proinflammatory cytokines (IL-6 and IFN-γ) but higher IL-10 levels as compared to those patients with severe liver fibrosis (F3-4)." (PMID 26742960, 2016). "Elevated levels of IL-17 and its receptors in response to liver damage may also promote the production of IL-1, IL-6, TGF-α, and collagen I that promote liver fibrosis." (PMID 25897319, 2015).
liver fibrosis (continued). "This may be associated with the crucial function that transforming growth factor (TGF)-β1 has in the development of liver fibrosis and the fact that cooperation between TGF-β1 and IL-6 may promote maturation of CD4+ T cells into Th17 cells." (PMID 25323532, 2015). "Thus in a mouse model of liver fibrosis, hepatic CD11c+ DCs expand 5-fold, inducing TNF-α, MCP-1 and IL-6 expression in co-cultured NK cells, with effects on inflammation, cell proliferation as well as fibrotic response." (PMID 24516640, 2014). "In the presence of inflammation, interleukin-6 (IL-6) could activate janus kinase 2 (JAK2)-signal transducer and activator of transcription 3 (STAT3) signaling pathway of which has been reported to lead to liver fibrosis." (PMID 41293246, 2025). "Among these inflammatory cytokines, IL-6, TNF, and TGF-β play crucial roles in maintaining immune responses, tissue repair, and homeostasis, serving as key pro-inflammatory and pro-fibrotic factors that activate hematopoietic stem cells and drive liver fibrosis." (PMID 40778202, 2025). "However, treatment with IL-6 prompts macrophages to secrete miR-223-enriched exosomes, reducing the expression of TAZ in liver cells via exosomal transfer, ultimately contributing to the attenuation of liver fibrosis in mice induced by HFD." (PMID 40129979, 2025). "In accord, our work in experimental steatohepatitis and hepatic fibrosis reveals an up-regulation of the TGFβ signaling pathway and proinflammatory cytokine expression (i.e. IL-1β, IL-6, and TNFα) in mice lacking CNP; moreover, many of these pathogenic processes can be reversed by CNP treatment." (PMID 39816244, 2025). "Notably, the interleukin-6 (IL-6) cytokine family plays a complex role in the onset and development of MAFLD, primarily through the modulation of lipid metabolism, insulin resistance, inflammatory responses, and liver fibrosis." (PMID 40969371, 2025). "However, the effect of curcumin on IL-6 in the hepatic fibrosis models was not statistically significant." (PMID 38781262, 2024). "Furthermore, pre- infection with T. spiralis markedly reduced S. mansoni- induced hepatic fibrosis, as evidenced by decreased collagen deposition, low expression of α-SMA, and significantly reduced levels of IL-17, IL-1B, IL-6, TGF-B, IL-23, and TNF-α compared to mice infected with S. mansoni only." (PMID 39439825, 2024). "However, the effects of curcumin on bcl-2 protein, IL-6 in hepatic fibrosis models and index of liver in mice were not statistically significant." (PMID 38781262, 2024). "However, the effects of curcumin on bcl-2 protein, IL-6, and mice index of liver in the hepatic fibrosis models were not statistically significant." (PMID 38781262, 2024). "Importantly, VSC-CDs demonstrated a mitigating effect on CCl4-induced liver fibrosis, as evidenced by the reduction in inflammatory cytokines (TNF-α, IL-6, IL-1β), elevation in antioxidant levels (SOD and GSH), and a decrease in lipid metabolites (MDA) to counteract oxidative stress damage." (PMID 38116381, 2023). "It has been reported that statins may play an important role in slowing the progression of liver fibrosis in patients with T2DM because statins can reduce hepatic expression of tumor necrosis factor-α (TNF-α), interleukin 6 (IL-6) and transforming growth factor-β (TGF-β)." (PMID 36899407, 2023). "This resulted in improved histology and decreased ALT, proinflammatory factor, and hepatic fibrosis gene mRNAs (Il1, Il6, Timp1 and Tgfb) and proteins expression (IL1β, IL6, α-smooth muscle actin (αSMA), COL1A1, TGFβ and TIMP1) revealing that P. distasonis could improve TAA-induced hepatic fibrosis." (PMID 37005411, 2023). "However, our findings did not demonstrate significant correlations of IL-6 with clinical parameters that assess liver function: elastography and liver fibrosis scores." (PMID 34447378, 2021).
liver fibrosis (continued). "However, more recent publications reveal negative effects of IL-6 which can directly induce transition of HSCs to myofibroblast-like cells, in hepatic fibrosis." (PMID 33841164, 2021). "Therefore, Hugan tablets may inhibit the activation of the PI3K-Akt signaling pathway through IL-6, AKT1, VEGFA, EGFR, and MAPK3, thereby inhibiting the activation of HSCs and delaying the occurrence of liver fibrosis." (PMID 34262454, 2021). "In this study, we showed that lnc-Lfar1 silencing alleviated liver injury-induced upregulation of LY6C, IL-1β, IL-6, TNF-α, MCP-1, CCL5 and CXCL10 in vivo and in vitro, suggesting that lnc-Lfar1 knockdown might be beneficial for preventing liver fibrosis by targeting these chemokines." (PMID 32071306, 2020). "For example, a study reported that CUR (200 mg/kg) could alleviate liver fibrosis in male rats by inhibiting the expression of inflammatory cytokines such as TNF-α, IL-6, and MCP-1 and eventually prevent the development and progression of obesity-related diseases." (PMID 33584555, 2020). "Decreasing the levels of IL-1β, IL-6, and TNF-α could alleviate CHI and hepatic fibrosis." (PMID 33144872, 2020). "Indeed, in a DEN-induced neonatal mice model, IL-6 knockout attenuated hepatocarcinogenesis, reassuring the importance of IL-6 axis in this process even in the absence of liver fibrosis." (PMID 30212575, 2018). "At the chosen time-point (week 17), we observed a clear liver fibrosis in both DEN doses in male mice (DEN10/CCl4 and DEN50/CCl4), characterized by increased collagen accumulation (Sirius red), HSCs activation (α-SMA), increased population of CD68+ macrophages and activation of COX-2/IL-6 axis." (PMID 30212575, 2018). "Neutralization of IL-9 in mice ameliorated hepatic fibrosis, attenuated the activation of hepatic stellate cells, reduced frequencies of Th9, Th17 and Th1 cells in spleen, and suppressed expression of IL-9, IL-17A, IFN-γ, TGF-β1, IL-6, IL-4 and TNF-α in plasma and liver respectively." (PMID 26728971, 2016). "The intricate relationships among TNF‐α, IL‐6, CCL2, and TGF‐β through positive feedback loops and synergistic interactions create a persistent fibrotic environment, suggesting that a multifaceted therapeutic approach may be necessary to address liver fibrosis effectively." (PMID 41487942, 2026). "This is in line with the evidence of the central role of inflammatory pathways in liver fibrosis progression in MASLD and suggests that epigenetic changes affecting SOCS3 could impact the expression of cytokines primarily involved in inflammation and fibrogenesis, such as IL-6 and MCP-1." (PMID 39941038, 2025). "Although one injection of lv-Fendrr did not cause obvious liver fibrosis (data not shown), hepatic α-SMA, the representative marker of HSC activation, was greatly upregulated, suggesting that the increase of Fendrr is implicated with HSC activation, most likely by inducing IL-6." (PMID 38762176, 2024). "In addition, our study showed that IL-6 levels were a good indicator of EHI even in the presence of an immune tolerance phase with normal ALT levels, and MCP-1 levels could reflect significant liver fibrosis at high levels of HBV DNA loads." (PMID 36389814, 2022). "Although the effect of BM-MSCs on IL6/STAT3 pathway was conducted in cancer and has shown that MSCs could promote progression of cancer through activation of IL6/STAT3 pathway, the immunomodulatory role of BM-MSCs on IL17A/IL6/STAT3 was not fully elucidated in liver fibrosis." (PMID 30346985, 2018). "There was a significant decrease in the protein levels of TNFα, IL‐6 and IL‐17 (P < 0.01) in CCI4 treated fibrosis‐induced mice injected with Exo‐181 compared to the liver fibrosis mouse model without exosome treatment." (PMID 28382720, 2017). "The stage of liver fibrosis did not correlate with the serum markers of inflammatory reaction (hsCRP, IL2, IL6, p>0.05)." (PMID 25350286, 2014).
liver fibrosis (continued). "Among participants with chronic HCV, mean log IL-6 was higher in magnitude among those with advanced hepatic fibrosis/cirrhosis, while mean log IGF-1 was lower in magnitude, compared to participants with chronic HCV who had no/minimal hepatic fibrosis." (PMID 40700400, 2025). "Interestingly, supplementation with DHBA failed to increase the level of ALT/AST, TNF-α/IL-6, or TGF-β1/α-SMA/COL1A1 in CCl4-challenged GPR81 KO mice, suggesting that the detrimental effects of DHBA on CCl4-induced liver fibrosis depend on GPR81." (PMID 38982366, 2024).
pulmonary fibrosis (410 papers, 2005 to 2026). Chronic progressive interstitial lung disorder characterized by the replacement of the lung tissue by connective tissue, leading to progressive dyspnea, respiratory failure, or right heart failure. "In particular, IL-6 has been shown to be involved in chronic lung inflammation with the potential to cause pulmonary fibrosis and long-term respiratory issues." (PMID 40137715, 2025). "Nevertheless, in bleomycin-induced pulmonary fibrosis mice models, Axl deficiency leads to reduced IL-6 and TNFα expression and a decrease in M2-like macrophage differentiation in lung tissue." (PMID 41155824, 2025). "Conversely, IL-6-deficient mice in bleomycin- induced lung fibrosis showed reduced pulmonary fibrosis and inflammation." (PMID 41009491, 2025). "CRP (rho:0.449, p=0.009), LTα (rho:0.487, p=0.004), and IL-6 (rho: 0.400, p=0.021), all of which are associated with lung fibrosis were found to correlate with Gal9 levels." (PMID 40977722, 2025). "Aditionally, our analysis revealed that the increase in IL-6 at the 3-month evaluation represents a risk factor for lung fibrosis." (PMID 39767173, 2024). "Studies have shown that skin and lung fibrosis in a scleroderma mouse model was attenuated in B-cell-specific IL-6-deficient mice." (PMID 39080112, 2024). "IL-6 is highly associated with inflammation, lung injury, and exacerbation of lung fibrosis/remodeling." (PMID 39192275, 2024). "High-titer IL-6 c-aAb were associated with increased odds for pulmonary fibrosis diagnosis in men [OR = 8.90 (IQR: 1.65–48.18), p = 0.040]." (PMID 39606243, 2024). "Other important mediators associated with lung fibrosis are legumain, osteopontin, IL-4, IL-6, IL-13, IL-17, TNF-α, Gal-1, Gal-3, PDGF, and FGFR-1." (PMID 38540252, 2024). "Lungs from IPF patients as well as the bleomycin-induced lung fibrosis in mice showed an increased pro-fibrotic mediator IL-6 implicated in the pathogenesis of PF." (PMID 37269594, 2023). "The study also identified the involvement of IL-6 and leptin in the association between adipose tissue and lung fibrosis." (PMID 38001499, 2023). "IL-6 has also been implicated in promoting fibroblast development and subsequently, pulmonary fibrosis." (PMID 37653422, 2023). "IL-6 deficient B cells induced an attenuation of dermal thickness, collagen expression and lung fibrosis." (PMID 35860745, 2022). "Using this model, it was shown that loss of IL-6 expression significantly improved skin and lung fibrosis." (PMID 36726987, 2022). "A study using a bleomycin-induced scleroderma model reported an accumulation of IL-6–producing B cells in the inflamed skin, and the skin and lung fibrosis were attenuated in IL-6 deficient mice." (PMID 35924234, 2022). "Mice with a B cell-specific deficiency in IL-6 exhibited attenuation of their skin and lung fibrosis, whereas those with a B cell-specific deficiency in IL-10 had severe skin and lung fibrosis." (PMID 35860745, 2022). "Earlier studies have documented the pro-inflammatory cytokines overexpression being associated with BLM induced lung fibrosis in animal models, including IL-1β, IL-6 and TNF-α." (PMID 35326173, 2022). "On the other hand, a decrease in pulmonary fibrosis and inflammation was observed in IL-6-deficient mice." (PMID 35203527, 2022). "Though little is known regarding IL-6 polymorphisms and the pathogenesis of idiopathic pulmonary fibrosis in SARS-CoV-2 infections, data tend to confirm that the IL-6 174 is associated with elevated inflammatory patterns in the outcome of SARS-CoV-2 pneumonia." (PMID 36428884, 2022). "EGFR+ SSc fibroblasts also expressed higher levels of interferon inducible genes (IFI27, BST2), which have been shown to correlate with SSc disease severity, and IL6, a profibrotic cytokine whose inhibition slows SSc-associated lung fibrosis." (PMID 36490328, 2022). "Il6-deficiency in mice improved recovery from lung fibrosis and ALI following bleomycin administration, but the underlying mechanism remains elusive." (PMID 35126382, 2021).